ANKS1A (ankyrin repeat and sterile alpha motif domain containing 1A)
Description:
Regulator of different signaling pathways. Regulates EPHA8 receptor tyrosine kinase signaling to control cell migration and neurite retraction (By similarity).
Synonyms: ANKS1; KIAA0229
Tractability: PROTAC: ubiquitination databases record sites on it.
Gene: Protein-coding gene on chromosome 6 (34,889,243 to 35,091,421, forward strand). Ensembl gene ENSG00000064999.
Subcellular location: Cytoplasm; Cell projection
Subcellular location (Human Protein Atlas): Nucleoplasm; Cytosol
Gene Ontology:
Molecular function: protein binding; ephrin receptor binding
Biological process: ephrin receptor signaling pathway; neuron remodeling; substrate-dependent cell migration
Cellular component: cytosol; neuron projection; cytoplasm
Genetic constraint (gnomAD): Loss-of-function variants: 51 observed, 117.4 expected, observed/expected ratio (o/e) 0.43, 90% interval 0.35 to 0.55. The upper end of that interval is the gene's LOEUF score, 0.55, which puts it in group 2 of 6, group 1 being the genes least tolerant of losing a copy. Missense variants: 1,107 observed, 1,451.5 expected, observed/expected ratio (o/e) 0.76, 90% interval 0.73 to 0.8. Synonymous variants: 584 observed, 595.74 expected, observed/expected ratio (o/e) 0.98, 90% interval 0.92 to 1.05.
Homologues: Orthologues: chimpanzee ANKS1A (99% identical), macaque ANKS1A (98% identical), dog ANKS1A (94% identical), rabbit ANKS1A (92% identical), pig ANKS1A (91% identical), mouse Anks1 (88% identical), rat Anks1a (88% identical), guinea pig ANKS1A (87% identical), tropical clawed frog anks1a (58% identical), Drosophila melanogaster CG4393 (33% identical), zebrafish anks1ab (26% identical), Drosophila melanogaster CG11168 (24% identical), and 1 more. Paralogues in human: ANKS1B (51% identical).
Diseases named in the same sentence as ANKS1A in open-access papers:
ANKS1A is named in the same sentence as 16 diseases in open-access papers, as found by Europe PMC text mining. Sharing a sentence is not in itself a finding about the gene and the disease. The quoted sentences say what the papers report.
Alzheimer disease (1 paper, 2023). A progressive, neurodegenerative disease characterized by loss of function and death of nerve cells in several areas of the brain leading to loss of cognitive function such as memory and language. "ANKS1A deficiency in an Alzheimer’s disease mouse model results in exacerbated Aβ pathology followed by cognitive impairments." (PMID 38123547, 2023). "Here, the authors report that ANKS1A promotes the LRP1-mediated Aβ clearance in brain endothelium, providing insights into the pathology of Alzheimer’s disease." (PMID 38123547, 2023).
breast carcinoma (1 paper, 2016). "To determine how directly Anks1a inhibits tumorigenesis in the mammary epithelium, we isolated primary mammary tumour cells (PMTCs) from MMTV-Neu females and measured their colony-forming ability on infection with Anks1a-specific shRNA lentivirus." (PMID 27619642, 2016). "We next used the SK-BR-3 human breast cancer cell line with ErbB2 amplification to see whether Anks1a plays a role in EphA2-mediated ErbB2 signalling." (PMID 27619642, 2016).
breast tumour (1 paper, 2016). "We further examined the effect of the Anks1a-null mutation in the context of the MMTV-Neu transgenic mouse model for human breast tumour formation." (PMID 27619642, 2016). "Together, these results indicate that the specific interaction between Anks1a and EphA2 is important for breast tumour growth in MMTV-Neu mouse model." (PMID 27619642, 2016).
cerebral amyloid angiopathy (1 paper, 2023). "Taken together, from our models of study, the results strongly suggest that ANKS1A loss is a risk factor for cerebral amyloid angiopathy (CAA) in humans." (PMID 38123547, 2023).
chronic sinusitis (1 paper, 2016). "Specifically, several SNPs mapping to ANK3 are highly represented in both the acute respiratory infection and the chronic sinusitis association results, and variants mapping to ANKS1A were associated with acute sinusitis." (PMID 27508393, 2016).
Cognitive impairment (1 paper, 2023). Abnormal cognition is characterized by deficits in thinking, reasoning, or remembering. "In the AD mouse model, ANKS1A deficiency exacerbated Aβ deposition in the brain endothelium, BBB breakdown and cognitive impairment due to the impaired cerebrovascular Aβ clearance." (PMID 38123547, 2023).
colon carcinoma (1 paper, 2016). "Since CT26 (colon carcinoma derived) cells endogenously express high levels of both Anks1a and EphA2, we used this cell line for studying the subcellular localization of Anks1a." (PMID 27619642, 2016).
coronary artery disease (1 paper, 2018). "In addition, our analyses suggested that genetic variations at the ANKS1A, COL4A2 and APOE loci previously found associated with coronary artery disease in the general population could have stronger effects in patients with type 1 diabetes." (PMID 29695241, 2018).
retinoblastoma (1 paper, 2018). A malignant tumor that originates in the nuclear layer of the retina. "The substrates of WNK1 such as MAPK1, OXSR1, STK39 (SPAK), and ANKS1A were identified to be phosphorylated in our study, but their phosphorylation status was unchanged in retinoblastoma compared to control retina tissues." (PMID 29914080, 2018).
cancer (1 paper, 2016). A tumor composed of atypical neoplastic, often pleomorphic cells that invade other tissues. "Anks1a is frequently overexpressed in various cancer cell types, and a recent a genome-wide association study named Anks1a among the top 17 genes with single-nucleotide polymorphisms associated with advanced-stage non-small cell lung cancer." (PMID 27619642, 2016). "Since we report the Anks1a ANK domain interacts with the TKD of EphA2, it may represent a novel therapeutic target for the treatment of cancer." (PMID 27619642, 2016).
tumour (1 paper, 2016). "Ectopic Anks1a PTB domain expression also inhibits the tumour growth potential of CT26 cells as measured by syngenic transplantation experiments." (PMID 27619642, 2016). "Together, our findings demonstrate Anks1a-regulated EphA2 ER export significantly enhances the level of EphA2 at the cell surface and consequently enhances tumour growth." (PMID 27619642, 2016). "To investigate EphA2-mediated tumour growth, we used CT26 cell lines expressing one of two shRNAs (shRNA-17 or -21) specific to Anks1a (first panel)." (PMID 27619642, 2016). "Interestingly, ectopic expression of the Anks1a PTB domain has a much larger effect on Erk activity and tumour growth than Anks1a-specifc shRNA expression, suggesting that the Anks1a PTB domain is a strong dominant-negative inhibitor of Anks1a in CT26 cells." (PMID 27619642, 2016). "Although control CT26 cells effectively induce tumour formation within 2 weeks, CT26 cells depleted for Anks1a do not." (PMID 27619642, 2016).
ANKS1A also shares sentences with these, for which no sentence is quoted: brain tumor (1 paper); colorectal cancer (1); infection (1); schizophrenia (1); type 1 diabetes (1).